CXCL1 (C-X-C motif chemokine ligand 1)
Diseases named in the same sentence as CXCL1 in open-access papers (continued):
Sharing a sentence is not in itself a finding about the gene and the disease.
Sepsis (continued). "CXCL1 levels also tend to increase in sepsis patients, with an increase close to statistical significance relative to healthy individuals (p = 0.07)." (PMID 36613652, 2022). "CXCL1 production in the brain in sepsis is carried out by astrocytes and microglial cells, in a process dependent on pro-inflammatory cytokines." (PMID 36613652, 2022). "BPF treatment indeed inhibited the CLP-induced production of IL-6, TNF-α, and CXCL1 by sepsis-induced peritoneal macrophages (consistent with the results in HUVECs and THP-1-macrophages)." (PMID 36361915, 2022). "CXCR1 and CXCR2 in human neutrophils are well established receptors for the neutrophil chemoattractant, IL-8, and others have shown modulated CXCL1 and chemokine receptor expression by IL-33 in bacterial infections and sepsis in animal models." (PMID 34266437, 2021). "By 4 h p.i., 7 additional cytokines were significantly reduced, including TNF, IL-6, and CXCL1 (KC) which have major roles in sepsis pathogenesis." (PMID 34873199, 2021). "In the study of chemokine-mediated NETs formation, CXCL1 was reported to rescue alcohol-induced immune disorders in polymicrobial sepsis by promoting the formation of NETs." (PMID 34721432, 2021). "Reportedly, treatment with IL-34 also assisted to protect mice against polymicrobial sepsis by inducing the expression of cytokines (IL-6, TNFα) and chemokines (CXCL1, CCL2)." (PMID 32231137, 2020). "Regardless of the cellular origin, we found that the inflammatory response to sepsis was dependent on CXCL1 as evidenced by neutrophil influx, bacterial clearance, and mortality." (PMID 28922428, 2017). "Taken together, our data unveils novel mechanisms underlying acute alcohol-induced dysregulation of the immune responses in polymicrobial sepsis, and CXCL1 is a critical mediator to rescue alcohol-induced immune dysregulation in polymicrobial sepsis." (PMID 28922428, 2017). "We have also shown that the expression of key inflammatory cytokines and chemokines was dependent upon CXCL1 during polymicrobial sepsis." (PMID 28922428, 2017). "Simultaneously, a study also showed that hepatic gp130 signaling was required for mobilization and accumulation of MDSCs during polymicrobial sepsis and that hepatic acute-phase proteins serum amyloid A and Cxcl1/KC cooperatively play a role in the process." (PMID 21394214, 2011). "Several other products implicated in the pathogenesis of sepsis were also induced by this treatment, including IL-12p40, CCL5/RANTES, CXCL1/KC, CCL9/MIP-1γ, CXCL2/MIP-2, P-Selectin, TIMP-1 and CCL2/MCP-1." (PMID 19284588, 2009). "These in vivo data strongly support our in vitro findings that alveolar epithelial cells are a major source of CXCL1 after LPS stimulation, positioning alveolar epithelial cells as a key initiator driving neutrophil recruitment during sepsis." (PMID 40953301, 2025). "This epithelial‐specific regulation mechanistically links RIPK1 to neutrophil‐mediated injury and positions RIPK1 as a critical orchestrator of CXCL1‐driven neutrophilic inflammation, highlighting its unique role in translating epithelial stress signals into alveolar injury during sepsis." (PMID 40953301, 2025). "This peritoneal vicious cycle that includes NET formation, IL-17A, CXCL-1/CXCL-2 that may amplify organ injury in sepsis." (PMID 41041553, 2025). "In the second acute-phase response model, the septicemia-like model, an increase in hepatic CXCL1 and CXCL8 gene expression of a similar magnitude as that in the other model was measurable after intraperitoneal (i.p.)injection of LPS, but upregulation declined earlier." (PMID 35336843, 2022). "Moreover, the chemokine CXCL-1 is an important neutrophil chemoattractant during inflammation in general and sepsis in particular." (PMID 35625756, 2022). "Moreover, the secretion of PSM-mec toxins increased cytokine expression (IL-1β, TNF-α and the mouse IL-8 homologue CXCL1), leading to elevated sepsis severity in a murine model of sepsis." (PMID 35055041, 2022).
Sepsis (continued). "In the setting of sepsis, the locally produced chemokines, such as CXCL1, CXCL2, and CXCL6, could lead to neutrophil chemotaxis and subsequent neutrophil infiltration by ligand-receptor binding." (PMID 35345558, 2022). "A recent study reported that CXCL-1 could induce neutrophils to infiltrate the sites of bacterial infection and was involved in the granulopoiesis and mobilization of neutrophils in sepsis." (PMID 32766286, 2020). "In accordance with organ dysfunction in the FtHfl/fl mice, 24 h after CLP surgery, there was a significant increase in the levels of cytokines that have been implicated in the pathogenesis of sepsis, including the pro-inflammatory cytokines, TNF-α, IFN-γ, IL-6, IL-12, CXCL1, IL-1β, and IL-2." (PMID 30804939, 2019). "CXCL1/KC is a neutrophil chemokine that is known to play an important role in neutrophil recruitment in a variety of direct and indirect lung injury models including sepsis, pancreatitis, and ventilator-induced lung injury." (PMID 28923112, 2017). "Therefore, our study provides novel mechanisms underlying acute alcohol-induced dysregulation of the immune responses in sepsis which can be rescued by CXCL1." (PMID 28922428, 2017). "CXCL1 may also contribute to vascular dysfunction during sepsis." (PMID 40806258, 2025). "Thus, we evaluated the cytokine production ability of BM monocytes from naïve and from LPS-treated mice and found that BM monocytes from LPS-treated mice showed significantly lower production of TNF-α, a representative cytokine involved in sepsis induction, and CXCL1." (PMID 39040105, 2024). "The P2X7 receptor activation is involved in chemokine (C-X-C motif) ligand 1 (CXCL1) recruitment and brain endothelial activation, which promotes blood-brain barrier (BBB) leakage and microglial cell activation, causing neuroinflammation in the acute phase of sepsis (24 h)." (PMID 37153798, 2023). "For instance, AM anti-inflammatory polarization in a LPS model of sepsis was TNF dependent, as AMs exposed to TNF exhibited diminished phagocytosis, superoxide anion (O2−) and CXCL1 production, with reduced neutrophils recruitment." (PMID 40624927, 2025). "In polymicrobial sepsis, the activation of the NFAT pathway led to an increase in the expression of chemokines (CXCL1, CXCL2 and CXCL5) and neutrophil migration and infiltration in the lung, whereas FK506 impaired central migration of neutrophils." (PMID 38242872, 2024). "Regarding neutrophils, the levels of Tnfα, IL-6, IL-1β, CXCL1, CXCL2, CCL5, and CXCL10 increased significantly in response to sepsis sEVs compared with those from the control group and healthy individuals." (PMID 38910259, 2024). "We found IL-24, CXCL1, TSLP and IL-8 were significantly different between the NEC and sepsis groups." (PMID 36806964, 2023). "During the course of LPS sepsis (0–36 hpi), most PICCs reached the first and second peak at 6 and 16 hpi, respectively, with IL-6, IL-18, CCL5, CCL7 and CXCL1 sustaining at plateau at 36 hpi." (PMID 37332010, 2023). "For example, blocking S100A9 with the inhibitor ABR-238901 greatly attenuates the CLP-induced infiltration of neutrophils, formation of edema, and expression of Mac-1, CXCL1, CXCL2 and IL-6 in the plasma or lung and improves sepsis-induced lung injury." (PMID 36768433, 2023). "Our results showed that genes such as IFN-γ, TNF-α, IL-6, MIP-2, IL-10, KC (CXCL1), CCL-2, MPO, MMP9, TLR2, and LCN2 were significantly upregulated in the lungs of sepsis-induced ARDS mice compared to control mice." (PMID 37822934, 2023). "CXCL-1 and CCL2 are chemokines crucial for the recruitment of neutrophils and monocytes during inflammation; and sepsis induces chemokine receptor expression on peripheral neutrophils." (PMID 35625756, 2022). "Studies on mice have shown that CXCL1/KC and CXCL2/macrophage inflammatory protein-2 (MIP-2) expression is increased in the kidney during sepsis." (PMID 36613652, 2022).
Sepsis (continued). "HU-308 has been reported to reduce plasma CXCL1, CXCL2, and TNFα in rodent models of sepsis, hepatic injury, and nephropathy." (PMID 36555499, 2022). "The median concentrations of TNF-α, IL-6, IL-8, MCP-1, and the chemokine CXCL1 in glioblastoma cyst fluid were far higher than previously published serum values for SARS covid-19 patients, patients with sepsis, and healthy controls." (PMID 35965529, 2022). "Mice with LPS-induced-sepsis who were treated with BPF had lower serum levels of IL-6, TNF-α, IL-1β, CXCL1, and CXCL2 than the control mice treated with BPF." (PMID 36361915, 2022). "For example, in a murine model of sepsis, amitriptyline decreased the serum levels of CCL2 and CXCL1 (KC, keratinocyte-derived chemokine)." (PMID 33945102, 2021). "AE prominently downregulated CXCL-1, CXCL-8, IL-6, TNF-α, Glu1, and HMGB1 mRNA expression but activated IL-1RN, IL-10, Sirt-1, and Nrf-2 mRNA expression in the lung during sepsis." (PMID 34493741, 2021). "As seen in sepsis, our findings showed decrease CXCR2 expression and great amount of systemic CXCL1 levels in serum of ethanol-fed mice after A. fumigatus infection." (PMID 32701055, 2020). "Anti-IL-17A antibodies downregulate CCL3, CXCL1, and IL-6 in cardiomyocytes of mice with sepsis induced by CLP, suggesting that IL-17A contributes to sepsis-induced cardiomyopathy." (PMID 32849528, 2020). "LPS-induced sepsis is less severe when injection at ZT10 than at ZT12, coinciding with a decrease in pro-inflammatory cytokines TNF-α, IL-6, and CXCL1 at ZT12, and increase in the anti-inflammatory cytokine IL-10." (PMID 31470863, 2019). "Congruently, administration of the neutrophil attractants CXCL1 and CXCL2 into the peritoneal cavity after inducing polymicrobial sepsis enhances both neutrophil recruitment and clearance of bacteria, as well as improving host survival." (PMID 28405616, 2017). "Here, we found increased serum IL-6, CXCL1, and HMGB1 levels in sepsis survivors 2 weeks post-CLP when compared to sham controls." (PMID 29326685, 2017). "IL-10, a negative regulator of inflammation, and CXCL-1, a chemokine involved in neutrophil migration, are also well-characterized serum markers of CLP sepsis severity." (PMID 26790027, 2016). "In agreement with the neutrophil recruitment data, CXCL1 and CXCL2 levels were similar in the three experimental groups in all tested time points after severe sepsis induction." (PMID 25084278, 2014). "While IL‐12B and CXCL‐1 levels were higher in sepsis DM mice compared to DM‐only mice, these differences were not statistically significant." (PMID 40654181, 2025). "In this study, we hypothesize that RIPK1 activation in type II alveolar epithelial cells (ATII) promotes CXCL1‐driven neutrophil recruitment via JAK1‐STAT3 signaling, independently of necroptosis, thereby exacerbating sepsis‐induced lung injury." (PMID 40953301, 2025). "As sepsis is a systemic intravascular infectious disease, during sepsis, the endothelial cells in the cerebrovascular blood vessels also produce various chemokines, such as CCL2, CCL3, CCL5, CXCL1, CXCL2, CX3CL1, and CXCL8." (PMID 38585633, 2024). "Some studies have shown that the levels of characteristic cytokines such as TNF‐α, IL‐6, IL‐1β, IL‐1α, IL‐12, IL‐17, CXCL1, CXCL2, MCP‐1, IL‐8, CXCL10, GM‐CSF, M‐CSF, and G‐CSF in patients with septicemia are significantly higher than those in normal volunteers." (PMID 36684101, 2023). "Conversely, several of these cytokines (IL‐1β, IL‐6, TNF‐α, CXCL1) were significantly elevated in AZ106‐treated mice compared to those subjected to CS alone, indicating a potential role for P2X7R in the modulation of the inflammatory response during sepsis." (PMID 35668576, 2022).
Sepsis (continued). "A previous study showed that blocking CXCR2, the main receptor of CXCL1 and CXCL2, effectively decreased alveolar accumulation of neutrophils in the CLP model of sepsis, demonstrating that CXC chemokines are important regulators of pulmonary infiltration of neutrophils in septic lung injury." (PMID 34884728, 2021). "In sepsis, CFH augments both CXCL1 mRNA and protein expression in the lung." (PMID 32012200, 2020). "Consistent with our in vivo sepsis lung tissue data, Fer-1 significantly attenuated LPS induced expression of proinflammatory cytokines IL-1β and IL-6, but not TNFα, as well as the chemokine CXCL1 and chemokine receptor CCR5." (PMID 41518848, 2026). "We detected a prominent effect of AE administration downregulating BALF levels of CXCL-1 (P < 0.05), CXCL-8 (P < 0.01), IL-6 (P < 0.05), IL-10 (P < 0.01), and TNF-α (P < 0.001) and upregulating BALF levels of IL-10 (P < 0.05) and IL-1RN (P < 0.05) during sepsis." (PMID 34493741, 2021). "Thus, we assessed whether acute ethanol challenge via gavage diminishes antibacterial host defense in a sepsis model using cecal ligation and puncture (CLP) and whether this immunosuppression can be rescued by exogenous CXCL1." (PMID 28922428, 2017). "In addition, others have shown a discordance between CXCL1 and BAL cell counts with a high CXCL1 and low BAL cell count in murine models of sepsis or endotoxemia suggesting that lung CXCL1 expression may not correlate with BAL cell counts in indirect models of lung injury." (PMID 32012200, 2020). "We found that TSH radically attenuated the release of IL-6, CXCL-1 and MCP-1 in the secondary CLP-induced sepsis but TH alone did not." (PMID 30291296, 2018). "In our model, septic DM mice exhibited trends toward elevated levels of pro‐inflammatory markers, including IL‐12B, CXCL‐1, and TNF‐α, and reduced IL‐4 levels compared to mice with sepsis or DM alone; however, these differences did not consistently reach statistical significance." (PMID 40654181, 2025).
colon carcinoma (62 papers, 2008 to 2026). "For examples, the CXCL1/CXCR2 axis has been implicated in colon cancer metastasis and gastric cancer progression." (PMID 37953876, 2023). "In inflammation and/or cancer of the colon, the expression of CXCL1 and CXCL2 is increased, which causes the chemotaxis of MDSCs." (PMID 35163326, 2022). "The results showed that CXCL1 overexpression in colon cancer cells increased the infiltration of tumor-associated macrophages (TAMs), while decreasing the CD4 and CD8 cells around the tumor." (PMID 36434686, 2022). "In colon cancer tissues, higher mRNA expression of CXCL1, 3, 8, 10, and 14 was significantly associated with longer OS (p < 0.05)." (PMID 34439306, 2021). "In colon cancer, increased CXCL1 expression is associated with tumor size, stage, depth of invasion, lymph node metastasis, and patient survival." (PMID 32730361, 2020). "In human colon carcinoma cell lines, CXCL1 and its receptor CXCR2 have been associated with metastatic potential and are thought to modulate cell proliferation and invasion in both an autocrine and paracrine manner." (PMID 27682863, 2016). "Finally, there are also articles that indicate that high CXCL1 expression in the tumor is associated with a better prognosis for the colon cancer patient." (PMID 37408240, 2023). "However, in the TCGA database, highly expressed CXCL1 is associated with better survival in colon cancer, and this is consistent with a previous report that overexpression of CXCL1 positively correlates with improved survival." (PMID 32337262, 2020). "However, the source of elevated CXCL1 and the underlying mechanisms responsible for colon cancer progression remain elusive." (PMID 30115896, 2018). "Moreover, elevated CXCL1 expression has recently been associated with an invasive phenotype in human colon carcinoma cells and down-regulation of the matrix protein fibulin-1." (PMID 18578857, 2008). "When the CXCL1 gene was silenced in colon cancer cells, a slowdown in their growth was observed; the opposite effect was obtained when it was overexpressed." (PMID 40943634, 2025). "In support of this, inhibition of the CXCL1/CXCR2 pathway has been reported to reduce the incidence of liver metastases originating from colon cancer." (PMID 40943634, 2025). "Among the several CXCR2 ligands, Cxcl1 mRNA was abundantly produced in all mouse colon cancer cell lines, although few levels of Cxcl1 mRNA were detected in IEC-6 cells." (PMID 38750114, 2024). "Exosomal RNA derived from tumor stem-like cells stimulates neutrophils to promote colon cancer tumorigenesis by secreting CXCL1 and CXCL2." (PMID 39100676, 2024). "Recent research has also revealed the significant involvement of CXCL1 in colon cancer progression, where it facilitates cancer development through the activation of the NF-κB/P300 signaling pathway." (PMID 38791448, 2024). "Some studies show that CXCL1 expression is higher in colon cancer tumors of elderly patients older than 65 years compared to patients younger than 65 years, and at least one study shows an inverse relationship." (PMID 37408240, 2023). "Some studies on colon cancer have shown that the higher the tumor stage is, the lower the level of CXCL1 in the tumor." (PMID 37408240, 2023). "In the in vivo colon cancer transplantation tumor model, treatment with the P300 inhibitor C646 significantly inhibited the growth of CXCL1-overexpressing colon cancer." (PMID 36434686, 2022). "In this part, we studied the effect of CXCL1 on the proliferation of colon cancer cells by CCK-8 and clone formation assays." (PMID 36434686, 2022). "The results showed that CXCL1 overexpression significantly promoted the migration of colon cancer cells, while CXCL1 knockout significantly inhibited the migration of colon cancer cells." (PMID 36434686, 2022). "CXCL1 promotes colon cancer development through activation of NF-κB/P300, and that CXCL1-based therapy is a potential novel strategy to prevent colon cancer development." (PMID 36434686, 2022).